IL6R (interleukin 6 receptor)
Diseases named in the same sentence as IL6R in open-access papers (continued):
Sharing a sentence is not in itself a finding about the gene and the disease.
prostate tumor (7 papers, 2017 to 2022). "It has been found that prostate tumor cells produce large amounts of IL-6 and express its receptors, IL-6R (gp80) and gp130, allowing them to respond in an autocrine manner to IL-6." (PMID 30134795, 2018). "The homing levels of targeted Nluc-27.pepL were further enhanced in THP-1 cells, suggesting that this protein might be able to accumulate at prostate tumors expressing the targeting receptor IL-6Rα." (PMID 35200430, 2022). "We previously examined a first-generation IL-27 targeted at the C-terminus with a short ‘peptide L’ (pepL, LSLITRL), which binds the interleukin 6 receptor α (IL-6Rα) that is upregulated in tumor cells in order to reduce prostate tumor growth (IL-27pepL or 27pepL)." (PMID 35200430, 2022). "In another recent report, we discovered the promise of a new IL-27 cytokine, targeted at the C-terminus with a short ‘peptide L’ (pepL, LSLITRL), which binds the interleukin 6 receptor α (IL-6Rα) upregulated in tumor cells for reducing prostate tumor growth (IL27pepL or 27pepL)." (PMID 34209203, 2021). "Endothelial cells do not express IL-6R, so IL-6 regulates endothelial function only through transsignaling, being involved in multiple biologic processes in prostate tumors." (PMID 35464825, 2022).
anemia (6 papers, 2021 to 2023). A reduction in the number of red blood cells, the amount of hemoglobin, and/or the volume of packed red blood cells. "Palladium nanoplate-based IL-6R antagonists have been designed to deliver tocilizumab to the liver for hepcidin suppression, which alleviates cancer-associated anemia and simultaneously inhibits tumor progression, partly due to corrected anemia, in murine models." (PMID 37208766, 2023). "This suggests that the anti-tumor efficacy of combined IL-6/IL-6R inhibition and ICIs for cancer-associated anemia may be tumor-dependent." (PMID 37208766, 2023). "Although the IL-6 pathway can be inhibited by either IL-6R or JAK inhibitors, our data suggest a more pronounced effect on anemia and inflammation with an anti-IL-6R treatment." (PMID 36544236, 2022). "Consistent with the decreased intestinal polyps in the anti-IL-6R-treated Apcmin/+Mlkl-/- mice, the anemia and thymus atrophy in the Apcmin/+Mlkl-/- mice were considerably alleviated after anti-IL-6R treatment." (PMID 33767595, 2021). "As expected, anti-IL-6R antibody therapy alleviated anemia and thymus atrophy in Apcmin/+Ripk3-/- mice." (PMID 33996591, 2021). "Treatment with an anti-IL-6 receptor (IL-6R) antibody reversed cancer-induced anemia." (PMID 37208766, 2023).
Anxiety (6 papers, 2023 to 2025). Intense feelings of nervousness, tension, or panic often arise in response to interpersonal stresses. "TCZ, a humanized IgG1 monoclonal antibody targeting the IL-6R, was shown to effectively reduce depressive and anxiety symptoms, with a sustained downward trend observed in more than 65% of RA patients." (PMID 40943274, 2025). "We specifically hypothesized that disrupted IL-6 secretion would be associated with perturbed amygdala emotional reactivity and greater depressive/anxiety symptoms; and that it would be predicted by the interactions between psychosocial stressors and IL6/IL6R." (PMID 37324818, 2023).
carotid atherosclerosis (6 papers, 2021 to 2025). A thickening and loss of elasticity of the walls of carotid arteries that occur with formation of atherosclerotic plaques. "Until recently, there is limited information regarding the association between IL6R gene polymorphisms and carotid atherosclerosis." (PMID 36060677, 2022). "Secondly, the mononucleotide polymorphism of the interleukin-6 receptor may be involved in the pathogenesis of carotid atherosclerosis and plaque vulnerability in males." (PMID 39479392, 2024). "IL6R signaling pathway could be an important therapeutic target for the prevention of carotid atherosclerosis and ischemic cerebrovascular events in male high-risk individuals." (PMID 36060677, 2022). "Thus, it is logical that the IL-6/IL6R gene polymorphisms could affect carotid atherosclerosis." (PMID 36060677, 2022). "Our results suggested that IL6R SNPs might participate in the pathogenesis of carotid atherosclerosis and plaque vulnerability in male individual." (PMID 36060677, 2022). "However, there is still a lack of evidence on the association between IL6R gene (rs4845625) polymorphism and carotid atherosclerosis." (PMID 36060677, 2022).
heart failure (6 papers, 2018 to 2025). Inability of the heart to pump blood at an adequate rate to meet tissue metabolic requirements. "IL-6R expression is also upregulated in heart failure and therefore underscores an additional therapeutic role of IL-6R blockers in lipotoxic cardiomyopathies." (PMID 30666212, 2018). "On the other hand, the long-term IL6 signaling or an over-production of IL6R protein could potentially lead to cardiovascular diseases followed by heart failure." (PMID 35514439, 2022).
liver cancer (6 papers, 2018 to 2023). An epithelial or non-epithelial malignant neoplasm that arises from the liver. "Qiupeng Zheng’s team at Fudan University found that overexpression of circCHIPK3 in liver cancer increased the expression of the interleukin 6 receptor (IL6R) by inhibiting the expression of miR-124, which resulted in tumor proliferation." (PMID 29626935, 2018). "Collectively, our experiments show that hepatic LEPR exerts a compensatory function in IL-6Rα-deficient mice in DEN-induced liver cancer development largely independent of changes in whole body metabolism." (PMID 30224299, 2018). "In this study, we have already revealed that IL-6Rα deficiency in lean mice was able to reduce DEN-induced HCC burden, but failed to completely prevent liver cancer development." (PMID 30224299, 2018). "Hepatic LEPR, whole body IL-6Rα, and combined deficiencies did not alter body composition, insulin sensitivity, and glucose tolerance in the DEN model of liver cancer in vivo." (PMID 30224299, 2018). "OSM could exert its biological effects in HepG2 also indirectly through the increase of membrane-associated and soluble IL-6R, although high concentrations of OSM may inhibit soluble IL-6R production, then possibly explain, at least in part, the opposite effects exerted by OSM in liver cancer." (PMID 36077744, 2022). "TM4SF5 interacts with IL6R, leading to STAT3 activation independent of IL6 in hepatic cancer cells." (PMID 34921636, 2021).
metastatic tumors (6 papers, 2009 to 2025). "It is maximized in rs8192284 IL-6R minor allele carriers and it is likely to promote hematogenous spread, causing a specific pattern of metastatic disease." (PMID 24886605, 2014). "A previous study revealed high expression of IL-6R in MDPs and demonstrated that metastatic tumors exhibiting elevated IL-6 levels prompted the differentiation of MDPs into M2-like macrophages." (PMID 40822347, 2025). "Anti-IL-6R improved helper T, cytotoxic T and natural killer (NK) cells in the lymphatic system and decreased Tregs in the recurrent and metastatic tumors." (PMID 38505617, 2024).
non-small cell lung carcinoma (6 papers, 2013 to 2024). A group of at least three distinct histological types of lung cancer, including non-small cell squamous cell carcinoma, adenocarcinoma, and large cell carcinoma. "In gefitinib-resistant non-small-cell lung cancer, IL-6R/JAK1/STAT3 signaling activation leads to de novo resistance to irreversible EGFR inhibitors." (PMID 27861147, 2017). "It has also been demonstrated that tocilizumab has anticancer potency via apoptosis induction as an agonistic IL-6R regulator and may be utilized as a new target molecule for non-small-cell lung cancer (NSCLC)." (PMID 28349061, 2017).
sarcoma (6 papers, 2012 to 2024). A usually aggressive malignant neoplasm of the soft tissue or bone. "In particular, the intestinal tumors (colon and rectal cancers), sarcoma, thymoma, uterine carcinosarcoma, and large B-cell lymphoma showed a strong IL6R down-regulation (FC ≤ −5)." (PMID 34576335, 2021). "T‐cells in the sarcoma microenvironment exhibited elevated levels of cytotoxicity (GZMB, GNLY and KLRD1), exhaustion (HAVCR2, CD38, CD160, CXCL13 and CX3CR1), and inflammation (IL33, PPARG, IL6R and SOCS3), suggesting an activated but exhausted phenotype." (PMID 39658531, 2024). "Despite expression of IL-6R and IL-6ST on EwS cell lines, IL-6 did not modulate expression of immunogenic markers on pediatric sarcoma cell lines." (PMID 39723214, 2024). "This suggests that IL-6R-pSTAT3 signaling is not involved in the upregulation of immunogenic markers in pediatric sarcomas but prevents apoptosis and promotes migration in pediatric sarcomas." (PMID 39723214, 2024).
triple-negative breast carcinoma (6 papers, 2019 to 2024). An invasive breast carcinoma which is negative for expression of estrogen receptor (ER), progesterone receptor (PR), and human epidermal growth factor receptor 2 (HER2). "Currently, there is an ongoing EMPOWER (NCT04333706) clinical trial of the combination of sarilumab (IL-6R inhibitor) plus capecitabine in triple-negative breast cancer patients in stage I-III with high-risk residual disease." (PMID 38398148, 2024). "In triple-negative breast cancer, the tumor suppressor miR-34a suppresses the expression of IL-6R and attenuates the role of the MCT-1 gene in epithelial-mesenchymal transition (EMT)." (PMID 38523627, 2024).
adenoma (5 papers, 2011 to 2025). A neoplasm arising from the epithelium. "In addition, in nonfunctioning adenomas, interleukin 6 receptor (IL-6R)/Janus kinase 2 (JAK2)/STAT3/matrix metallopeptidase 9 (MMP9) and phosphatidylinositol 3-kinases (PI3K) have been discovered to be involved in the PI3K/AKT pathway." (PMID 40299639, 2025).
AIDS (5 papers, 2018 to 2025). A syndrome resulting from the acquired deficiency of cellular immunity caused by the human immunodeficiency virus (HIV). "We also found significant associations between increased levels of EVs bearing PD-L1, CD40, TNF-RII and/or IL-6Rα with AIDS-NHL risk and more specifically with the development of non-CNS AIDS-NHLs." (PMID 37809067, 2023). "The results described in this study show that EVs bearing PD-L1, CD40, TNF-RII and/or IL-6Rα are significantly associated with AIDS-NHL risk and thus, may serve as biomarkers of AIDS-NHL." (PMID 37809067, 2023). "We observed significantly higher levels of EVs bearing PD-L1, CD40, TNF-RII and/or IL-6Rα in AIDS-NHL cases compared with controls." (PMID 37809067, 2023). "In this study, we were interested in measuring IL-6Rα in EVs as IL-6 levels are significantly elevated in HIV-infected individuals years prior to an AIDS-NHL diagnosis." (PMID 37809067, 2023). "Elevated levels of EVs bearing PD-L1, CD40, TNF-RII and/or IL-6Rα were observed in serum of HIV+ pre-AIDS-NHL cases compared to HIV+ controls." (PMID 37809067, 2023). "The elevated levels of EVs bearing IL-6Rα in pre-AIDS-NHL cases may bind cell membranes through receptor-ligand interactions and induce signaling in recipient cells." (PMID 37809067, 2023). "Further assessing correlations between EVs and soluble PD-L1 (or soluble forms of CD40, TNF-RII, and IL-6Rα), immunomodulatory cytokines/chemokines, and/or circulating immune cells may elucidate additional factors driving the development of AIDS-NHL." (PMID 37809067, 2023). "We then evaluated any associations between blood circulating EVs expressing the different immune cell surface markers (PD-L1, CD40, CD40L, B7-H3, TNF-RII, IL-6Rα, ICAM-1 or FasL) and tumor subtype of AIDS-NHL patients." (PMID 35655072, 2022).
breast tumor (5 papers, 2018 to 2024). "Increased expression of these cytokines, or the ligand-specific receptors IL-6R and IL-11RA, in breast tumors positively correlate to disease progression and poorer patient outcome." (PMID 35053592, 2022). "Our current results are in accordance with previously published studies and indicate that IL-6/IL-6R mediated signaling is a critical therapeutic target for inhibiting early stage breast tumor progression." (PMID 30134951, 2018). "Furthermore, it is worth noting that, in breast tumors in different BMI situations, inflammatory genes expression was positively correlated with interleukin-6 receptor gene expression." (PMID 34573003, 2021). "Both anti-IL-6R and anti-PD-L1 significantly suppressed CD4(+)/CD25(+) Tregs but outscored IgG2b, κ in the infiltration of CD8(+) CTLs in the recurrent breast tumors, suggesting the effective anti-tumor immunity." (PMID 38505617, 2024).
cardiac hypertrophy (5 papers, 2015 to 2022). "Many previous reports have demonstrated that IL‐6/IL‐6R signaling induces cardiac remodeling including myocardial hypertrophy." (PMID 32302067, 2020). "Double-transgenic mice overexpressing human IL-6 and soluble IL-6R showed no myocardial phenotype at the age of two months but developed cardiac hypertrophy at five months of age, suggesting that cardiac remodeling requires chronic exposure to IL-6/IL-6R signaling." (PMID 35163735, 2022). "IL-6 not only binds to IL-6R on the surface of cardiomyocytes and induces myocardial hypertrophy via the MAPK and CaMKII-STAT3 pathways but also binds to IL-6R on the surface of cardiac fibroblasts and activates them." (PMID 36299447, 2022).
delirium (5 papers, 2014 to 2025). A disorder characterized by confusion; inattentiveness; disorientation; illusions; hallucinations; agitation; and in some instances autonomic nervous system overactivity. "A study investigating Interleukin-6 (IL-6), Interleukin-8 (IL-8), and Interleukin-6 Receptor (IL-6R) genetic variations and delirium, found no polymorphisms associated with delirium." (PMID 24795632, 2014). "Plasma IL-6R was measured in a randomly chosen subset of animals (n = 10/group) to confirm differences in delirium-like phenotypes were not driven by receptor density." (PMID 36380004, 2022).
dermatitis (5 papers, 2019 to 2025). An inflammatory process affecting the skin. "When evaluated both clinically and histologically at day 7, treatment with anti-IL-17A antibody improved the dermatitis in both PD-1−/− and WT mice to a level equivalent to treatment with anti-IL-6R antibody." (PMID 33060784, 2020).
endothelial dysfunction (5 papers, 2019 to 2025). In vascular diseases, endothelial dysfunction is a systemic pathological state of the endothelium (the inner lining of blood vessels) and can be broadly defined as an imbalance between vasodilating and vasoconstricting substances produced by (or acting on) the endothelium. "These included genes such as CLNS1A, UGP2, RNF216, PHGDH, CKAP4, and IL6R, many of which are known to participate in inflammatory pathways, oxidative stress, and endothelial dysfunction." (PMID 41262879, 2025). "Specifically, this cluster of correlation has high levels of serum occludin, IL-6 receptor (IL-6R), soluble intercellular adhesion molecule-1 (sICAM-1) and vascular endothelial (VE)-cadherin, with potential inflammatory-induced endothelial dysfunction." (PMID 39182041, 2024). "In this study, we demonstrate the relationship between miR-451a and IL6R/STAT/TF signaling pathway in the process of SiNPs-induced endothelial dysfunction and pre-thrombotic state." (PMID 30975181, 2019). "The research suggested that targeting the FKSG29/miR-23a-3p/IL6R pathway could be a novel therapeutic strategy for OSA-induced endothelial dysfunction." (PMID 38672697, 2024). "Differently, the other cluster had high levels of serum occludin, IL-6R, soluble intercellular adhesion molecule-1 (sICAM-1) and VEC, with potential inflammatory-induced endothelial dysfunction." (PMID 39182041, 2024).
Hepatitis (5 papers, 2008 to 2019). Inflammation of the liver. "Recent studies showed that IL-6-/- mice exhibited signs of liver inflammation, and when the IL-6R was deleted only in hepatocytes, mice developed liver inflammation, which could be reduced by Tnf-alpha blockade, suggesting a pivotal balance of IL-6 and Tnf-alpha signalling in the liver." (PMID 27333268, 2016). "We identified 7 proteins that significantly differentiate HCC patients from hepatitis patients (p < 0.05) (AFP, CTNNB, CSF1, SELL, IGFBP6, IL6R, and VCAM1)." (PMID 19578489, 2008).
influenza (5 papers, 2013 to 2023). An acute viral infection of the respiratory tract, occurring in isolated cases, in epidemics, or in pandemics; it is caused by serologically different strains of viruses (influenzaviruses) designated A, B, and C, has a 3-day incubation period, and usually lasts for 3 to 10 days. "Although the previous reports of use of IL-6 blockers to treat CRS have shown mixed results, recent clinical data for α-IL-6 and α-IL-6R mAbs have shown early promise in human trials for treatment of severe influenza and corona virus infections." (PMID 33071786, 2020). "Anti-IL-6R treatment may diminish influenza vaccine antibody responses since IL-6 induces B cell differentiation into antibody-forming cells and T cells into effectors cells." (PMID 28784185, 2017). "Importantly, antigen-specific IL-6Rα+IL-7R+ CD4+ T cells emerge from the effector population at late time points post influenza infection." (PMID 26743592, 2016). "Importantly, at late time points post influenza infection, a population of antigen-specific IL-6Rα+IL-7R+ CD4+ T cells emerges coincident with a decline in the effector population." (PMID 26743592, 2016). ", antigen-specific IL6Rα+IL7R+ DP cells arises during the post-influenza-infection period." (PMID 26743592, 2016). "Our finding that antigen-specific effector CD4+ T cells upregulate the dual expression of IL-6Rα and IL-7R at late time points post influenza infection suggests that exposure to either cytokine could be a key determinant in further differentiation events and long-term cellular function." (PMID 26743592, 2016).
leukemia (5 papers, 2014 to 2025). A malignant (clonal) hematologic disorder, involving hematopoietic stem cells and characterized by the presence of primitive or atypical myeloid or lymphoid cells in the bone marrow and the blood. "The BCR/ABL fusion protein induces IL-6 expression in leukemia stem cells, and targeting IL-6R induces apoptosis in Philadelphia chromosome-positive acute lymphoblastic leukemia cells." (PMID 41293238, 2025).
lung adenocarcinoma (5 papers, 2014 to 2025). A carcinoma that arises from the lung and is characterized by the presence of malignant glandular epithelial cells. "PPAR-γ/NF-κB axis (upstream) and the IL-6/IL-6R (downstream) signaling pathway of aquaporin 3-mediated M2 macrophage polarization could regulate the proliferation, migration, and glycometabolism of lung adenocarcinoma." (PMID 40573305, 2025). "Given the tumor-promoting role of CD109 and of IL-6 in SCC and the recent findings that CD109 potentiates JAK/STAT3 signaling in lung adenocarcinoma and glioblastoma cells, it was important to establish whether CD109 regulates IL6Rα signaling in SCC and determine the mechanisms involved." (PMID 40317079, 2025). "Collectively, these results not only suggest that the IL-6/IL-6R/STAT3 may be used as molecular targets for the inhibition of IL-6-induced EMT, but also provide experimental evidence for the potential use of metformin in the treatment of lung adenocarcinoma." (PMID 24789104, 2014).
psychosis (5 papers, 2018 to 2023). "Our primary hypothesis is that inhibition of IL-6 signalling with a single intravenous infusion of anti-IL6R mAb, tocilizumab, in individuals with psychosis and elevated IL-6 at baseline, will attenuate symptoms of anhedonia and amotivation in patients with psychosis, relative to placebo." (PMID 36963796, 2023).